FADD (Fas associated via death domain)
Description:
Apoptotic adapter molecule that recruits caspases CASP8 or CASP10 to the activated FAS/CD95 or TNFRSF1A/TNFR-1 receptors. The resulting aggregate called the death-inducing signaling complex (DISC) performs CASP8 proteolytic activation. Active CASP8 initiates the subsequent cascade of caspases mediating apoptosis. Involved in interferon-mediated antiviral immune response, playing a role in the positive regulation of interferon signaling.
Synonyms: MORT1; GIG3; IMD90
Tractability: Small molecule: a structure with a bound ligand is known. Antibody: its Gene Ontology location is reachable by antibodies, with high confidence. PROTAC: ubiquitination databases record sites on it; its protein half-life has been measured.
Gene: Protein-coding gene on chromosome 11 (70,203,295 to 70,207,395, forward strand). Ensembl gene ENSG00000168040.
Subcellular location: Cytoplasm
Subcellular location (Human Protein Atlas): Cytosol; Nucleoplasm
Pathways (Reactome):
Programmed Cell Death: CASP8 activity is inhibited; Caspase activation via Death Receptors in the presence of ligand; Dimerization of procaspase-8; RIPK1-mediated regulated necrosis; Regulation by c-FLIP; Regulation of necroptotic cell death
Signal Transduction: FasL/ CD95L signaling; Regulation of TNFR1 signaling; TNFR1-induced proapoptotic signaling; TRAIL signaling
Immune System: NF-kB activation through FADD/RIP-1 pathway mediated by caspase-8 and -10; TLR3-mediated TICAM1-dependent programmed cell death; TRIF-mediated programmed cell death
Disease: Defective RIPK1-mediated regulated necrosis
Gene Ontology:
Molecular function: caspase binding; death effector domain binding; identical protein binding; protease binding; protein binding; protein-macromolecule adaptor activity; tumor necrosis factor receptor superfamily binding; death receptor binding; protein-containing complex binding; receptor serine/threonine kinase binding; signaling adaptor activity
Biological process: apoptotic process; apoptotic signaling pathway; cellular response to mechanical stimulus; death-inducing signaling complex assembly; defense response to virus; extrinsic apoptotic signaling pathway; extrinsic apoptotic signaling pathway via death domain receptors; necroptotic signaling pathway; positive regulation of apoptotic process; positive regulation of canonical NF-kappaB signal transduction; positive regulation of extrinsic apoptotic signaling pathway; positive regulation of interleukin-8 production; positive regulation of macrophage differentiation; positive regulation of proteolysis; positive regulation of transcription by RNA polymerase II; positive regulation of tumor necrosis factor production; positive regulation of type I interferon-mediated signaling pathway; TRAIL-activated apoptotic signaling pathway; lymph node development; negative regulation of activation-induced cell death of T cells; positive regulation of activated T cell proliferation; positive regulation of adaptive immune response; positive regulation of CD8-positive, alpha-beta cytotoxic T cell extravasation; positive regulation of innate immune response; positive regulation of T cell mediated cytotoxicity; and 16 more
Cellular component: caspase complex; CD95 death-inducing signaling complex; cytoplasm; cytosol; death-inducing signaling complex; nucleoplasm; plasma membrane; ripoptosome; cytoplasmic side of plasma membrane; cell body; protein-containing complex
Genetic constraint (gnomAD): Loss-of-function variants: 3 observed, 3.98 expected, observed/expected ratio (o/e) 0.75, 90% interval 0.34 to 1.72. That is too few expected variants to judge how well the gene tolerates losing a copy. Missense variants: 240 observed, 270.05 expected, observed/expected ratio (o/e) 0.89, 90% interval 0.8 to 0.99. Synonymous variants: 133 observed, 120.61 expected, observed/expected ratio (o/e) 1.1, 90% interval 0.96 to 1.27.
Gene-disease validity (ClinGen):
ClinGen rates the evidence that FADD causes each of these diseases.
FADD-related immunodeficiency (autosomal recessive): Moderate.
Homologues: Orthologues: chimpanzee FADD (98% identical), macaque FADD (94% identical), pig FADD (75% identical), dog FADD (72% identical), guinea pig FADD (68% identical), rat Fadd (68% identical), mouse Fadd (68% identical), tropical clawed frog fadd (39% identical), zebrafish fadd (32% identical).
Diseases named in the same sentence as FADD in open-access papers:
FADD is named in the same sentence as 201 diseases in open-access papers, as found by Europe PMC text mining. Sharing a sentence is not in itself a finding about the gene and the disease. The quoted sentences say what the papers report.
breast cancer (44 papers, 2006 to 2025). A primary or metastatic malignant neoplasm involving the breast. "In our study, Rheb downreglation by FADD deficiency was validated in human breast cancer cell lines MCF-7 and MDA-MB-231, as well as the impairment of mTORC1 activity." (PMID 27013580, 2016). "In this study, In Silico Analysis using Oncomine and Kaplan Meier plotter revealed that FADD is significantly up-regulated in breast cancer tissues and closely associated with a poor prognosis in patients with breast cancer." (PMID 27013580, 2016). "Colorectal cancer cell growth was inhibited by FADD expression and high FADD expression after neoadjuvant breast cancer treatment was associated with a good prognosis group in breast cancer." (PMID 24886289, 2014). "We further gauged the importance of AMPK activation and PEA15 Ser116 phosphorylation in its association with FADD in breast cancer cells." (PMID 25096718, 2014). "It would be intriguing to see whether the LOH of 8p12 breast cancer specimens correlates with an increased FADD-Pi which would support the functional effect of loss of DUSP26 in breast cancer." (PMID 33466673, 2021). "We found that FADD-positive cases showed a tendency towards better prognosis, which is concordant with the claim that high FADD expression is associated with better prognosis in breast cancer treatment." (PMID 24886289, 2014). "Hence, the authors propose FADD as a candidate biomarker for BRCA1-associated breast cancer." (PMID 31569512, 2019). "Total findings concluded that PARP cleavage, CYCS releasing, caspase-8, and enhanced expression of FADD authenticates the A. fragrantissima induces apoptosis in breast cancer MCF-7 cells." (PMID 38820323, 2024). "Conversely, an increased expression of FADD was observed in lung cancer, head and neck carcinoma, breast cancer, liver cancer, and urothelial cancer." (PMID 38542202, 2024). "CCAR1 expression is reduced in poorly differentiated breast cancers and FADD expression is downregulated during thyroid adenocarcinoma progression, with both cancers showing aberrant PI3K/AKT/mTORC1 pathway activation." (PMID 31285545, 2020). "Two upregulated (EpCAM, FADD) and two downregulated (NDRG1, αB-crystallin) proteins were associated with the progression of breast cancer." (PMID 31443698, 2019). "When MCF-7 breast cancer cells are treated with IL-24, key players in the Fas signaling pathway, such as Fas, FasL, and FADD, are upregulated, supporting previous studies that IL-24 activates apoptosis extrinsically." (PMID 30424508, 2018). "To understand how BRCA1 exerts its tumor-suppressive effects by regulating FADD in breast cancer cells, we next checked the effect of BRCA1 overexpression on FADD-related signaling." (PMID 29757984, 2018). "To gain an overview of FADD expression in human cancers, we performed analysis of published patient data using Oncomine and found that FADD mRNA level is significantly up-regulated in human breast cancer." (PMID 27013580, 2016). "FADD overexpression has been observed in head and neck squamous cell carcinoma, breast cancer, lung cancer and early-stage glottic squamous cell carcinoma and is associated with poor survival." (PMID 27286445, 2016). "In Curtis breast dataset with 2136 samples, FADD expression levels were upregulated in most of breast cancer tissues (n>1556, p=3.09E-13), compared with normal tissues (n=144)." (PMID 27013580, 2016). "The apoptosis induced by FADD overexpression also appeared in breast cancer cells, so RNA interference of FADD as a reasonable and practical approach of studying the effect of FADD protein expression level was widely used in our studies." (PMID 27013580, 2016). "Here, FADD interference down-regulated Rheb expression and repressed mTORC1 activity in breast cancer cell lines." (PMID 27013580, 2016). "Collectively, these findings indicate that up-regulated FADD predicts a poor prognosis in breast patients and is closely correlated with tumor progression in breast cancer." (PMID 27013580, 2016).
breast cancer (continued). "Here, we provided evidence that FADD overexpression correlated with poor outcome in human breast cancer for the first time." (PMID 27013580, 2016). "FADD overexpression has been observed in head and neck squamous cell carcinoma, breast cancer, lung cancer and early-stage glottic squamous cell carcinoma and correlates with poor survival rate." (PMID 27286445, 2016). "FADD, TMEM16A, and PPFIA1 gene expressions as a whole were associated with disease-free survival in breast cancer." (PMID 24886289, 2014). "FADD has been shown to play an important role in G2/M arrest and cell growth suppression induced by paclitaxel in breast cancer cells." (PMID 22348099, 2012). "Moreover, previous studies have demonstrated that the overexpression of BRCA1 in breast cancer cells that lack BRCA1 gene significantly upregulates FADD expression." (PMID 38542202, 2024). "The synergistic effect of the combination therapy of TQ and TRAIL significantly inhibit the genetic expressions of Bcl2 gene and upregulate the genetic expressions of Cas-8 and FADD genes up on breast cancer MCF-7 and MDA-MB-231 cell lines treated for 24 h with noted TQ or/and TRAIL concentrations." (PMID 34582654, 2021). "In addition, cycle and apoptosis regulator 1 (CCAR1) which is downregulated in breast cancers and FADD which exerts pro-apoptotic activity in breast cancer were shown to mediate Akt-induced senescence." (PMID 34298660, 2021). "In addition, we followed up 190 breast cancer patients for over 10 years and conducted a survival analysis for the positivity of expression (EpCAM, FADD, and αB-crystallin) or the level of expression (NDRG1) in the primary tumor sites." (PMID 31443698, 2019). "In addition, we also investigated potential correlations between FADD expression and the clinical pathological characteristics of 190 patients with breast cancer." (PMID 31443698, 2019). "Moreover, the regulatory mechanism of FADD in breast cancer metastasis warrants further investigation." (PMID 31443698, 2019). "Furthermore, higher expression levels of FADD were identified in patients with breast cancer, which were also correlated with a shorter survival time." (PMID 31443698, 2019). "Gene profiling of tumors by meta-analyses from microarray data sets shows that ANO1 and FADD, both located on chromosome 11q13, can serve as prognostic markers for breast cancer and head and neck cancer, indicating a critical role of ANO1 in FADD-mediated apoptosis." (PMID 29899325, 2018). "Since mTOR pathway is a key regulator of cell growth and proliferation, its deregulation might be an important clue for FADD function in breast cancer." (PMID 27013580, 2016). "Like FADD, high Rheb expression is also correlated to poor prognosis in human breast cancer." (PMID 27013580, 2016). "The protein level of Rheb had a good consistency with FADD expression in breast cancers." (PMID 27013580, 2016). "In this study, we first reported that FADD expression was remarkably higher in breast cancer and applied LC-MS/MS detection plus bioinformatics analysis to reveal that Rheb-mTORC1 pathway was dysregulated in breast cancer cells because of FADD knockdown." (PMID 27013580, 2016). "Notably, Rheb expression was also elevated in breast TMA as well as FADD, and reported to be correlated with poor prognosis in patients with breast cancer." (PMID 27013580, 2016). "In addition to the influence of selenium on caspase activation, it also promotes apoptosis by increasing Fas-associated death domain (FADD) expression and enhancement of caspase-8 recruitment for Fas and FADD (MCF7 breast cancer)." (PMID 25821636, 2015).
breast cancer (continued). "Moreover, all of the five cancers (100%) showing high level of p-FADD signal ablated the expression of both AK2 and DUSP26, underscoring a strong cross-talk for an inverse correlation between AK2/DUSP26 expression and p-FADD in the human breast cancers." (PMID 24548998, 2014). "Previously, we reported that MSA can induce FADD expression in MCF-7 breast cancer cells." (PMID 22348099, 2012). "As lymph node metastasis is well known to be strongly associated with prognosis of breast cancers, assessment of the phosphorylation status of JNK or FADD might provide relevant information for the efficacy of clinical therapy." (PMID 16450001, 2006). "However, phosphorylated JNK/FADD signals alone cannot lead to apoptosis induction, but rather to cell cycle arrest at G2/M in breast cancer cells." (PMID 16450001, 2006). "In addition, the expressions of phosphorylated JNK/FADD were examined using human breast cancer specimens by immunohistochemistry and evaluated with reference to clinicopathological parameters." (PMID 16450001, 2006). "Autophagy has been reported for lectins from Polygonatum odoratum on MCF-7 breast cancer cells, and its mechanism of action on L929 murine fibrosarcoma cells involves the activation of caspase 8, 9, and 3, and increased levels of expressed FasL and FADD death receptors." (PMID 37259433, 2023). "Thus, downregulation of AK2 expression seen here in the human breast cancers may regulate cell proliferation that is contributed by the phosphorylation of their substrate, FADD." (PMID 24548998, 2014). "For example, it was shown that MKRN1 E3 ligase is involved in the ubiquitination and degradation of FADD and can influence the rate of TRAIL-dependent apoptosis in breast cancer cells." (PMID 34830347, 2021). "The plots showed that the survival of breast cancer patients with reduced methylation of TSC1 (cg14350545), FADD (cg02794589), and TRADD (cg05178604) was significantly improved." (PMID 33194583, 2020). "In breast cancer, AK2 downregulation results in reduced interaction of AK2-DUSP26 complex with FADD and, subsequently, increased phosphorylated FADD levels in the nuclei of tumor cells, correlating with increased proliferation." (PMID 31569512, 2019). "Several nodes in this pathway emerged as potential direct targets of EGCG in breast cancer: JUN, FADD, NFKB1, Bcl-2, GNAO1, and MMP14." (PMID 28713815, 2017). "The results suggest that signaling proteins affected by EGCG in breast cancer, which include JUN, FADD, NFKB1, Bcl-2, GNAO1, and MMP14, are involved primarily in cell death and survival; DNA replication, recombination and repair; and the cell cycle." (PMID 28713815, 2017). "In particular, we identified JUN, FADD, NFKB1, Bcl-2, GNAO1, and MMP14 as potential targets of EGCG in breast cancer." (PMID 28713815, 2017). "To better understanding the FADD functions in breast cancer, we performed proteomics analysis by LC-MS/MS detection and found that Rheb–mTORC1 pathway was dysregulated in MCF-7 cells when FADD knockdown." (PMID 27013580, 2016). "In summary, we screened TMEM16A, FADD, and PPFIA1 expression in breast cancer and found that combination of the three gene expressions was associated with disease-free survival in invasive ductal carcinoma of the breast." (PMID 24886289, 2014). "We also have demonstrated that c-FLIPL interacts with DR5, FADD, and caspase-8 forming an Apoptotic Inhibitory Complex (AIC) in MCF-7 breast cancer cells." (PMID 25379355, 2013). "In this study, we demonstrate that α-TEA induces the accumulation of cell surface membrane ceramide, leading to co-localization with Fas, DR5, and FADD, followed by activation of caspases-8 and -9 and apoptosis in human MDA-MB-231 breast cancer cells." (PMID 20974006, 2010).
breast cancer (continued). "By CGH analysis of breast cancer samples, we identified CTTN and FADD as co-amplified with CCND1 at the 11q13 locus, and CHK1 as a marker for the frequently occurring distal 11q deletion." (PMID 18823530, 2008). "The result raises the possibility that FADD phosphorylation and upstream JNK activation can directly lead to the reduction of breast cancer metastasis." (PMID 16450001, 2006). "We also performed a similar analysis in the MDA-MB-468 breast cancer cell line, finding that Sam68 or FADD knockout alone did not lead to changes in cfDNA release." (PMID 38600351, 2024). "Based on our results showing FADD as a BRCA1 target, we further examined whether this finding is valid in breast cancer patients." (PMID 29757984, 2018). "Our network analysis also allowed us to identify several specific proteins that EGCG may help regulate in breast cancer, including JUN, FADD, NFKB1, Bcl-2, GNAO1, and MMP14." (PMID 28713815, 2017). "Dysregulation of this AK2/DUSP26/FADD signalling pathway does not have to be limited to breast cancer." (PMID 24548998, 2014). "In addition, immunohistochemical analysis using human breast cancer specimens showed a close correlation between phosphorylated JNK and FADD expression, both being significantly reduced in cases with metastatic potential." (PMID 16450001, 2006). "Based on these findings, we further found that the downregulation of DNA methylation of three CpG sites, TSC1 (cg14350545), FADD (cg02794589), and TRADD (cg05178604) could significantly prolong the survival of breast cancer patients (DNA methylation survival curves in the TCGA)." (PMID 33194583, 2020). "Therefore, we consider that upregulation of dephosphorylated FADD rather than reduction of phosphorylated FADD contributes to enhancement of invasion activity in breast cancer cells." (PMID 16450001, 2006). "We conclude that JNK-mediated phosphorylation of FADD plays an important role in the negative regulation of cell growth and metastasis, independent of the ER status of a breast cancer, so that JNK/FADD signals might be promising targets for cancer therapy." (PMID 16450001, 2006).